ALKBH5 (alkB homolog 5, RNA demethylase)
Diseases named in the same sentence as ALKBH5 in open-access papers (continued):
Sharing a sentence is not in itself a finding about the gene and the disease.
glioma (65 papers, 2018 to 2026). A benign or malignant brain and spinal cord tumor that arises from glial cells (astrocytes, oligodendrocytes, ependymal cells). "ALKBH5 loss fosters a more immunostimulatory microenvironment in glioma through an expanded T-cell presence-marked by increased CD4+and CD8+T lymphocyte counts and a higher CD8+/CD4+ ratio-coupled with a reduction in PD-L1 protein expression." (PMID 41522342, 2026). "The overexpression of ALKBH5 in glioma-associated mesenchymal stem cells (GBMSCs) promotes its radiation resistance by controlling homologous repair." (PMID 38473842, 2024). "In this study, two glioma subgroups were identified based on the expression of m6A regulators, and a risk signature (ALKBH5, IGF2BP3, KIAA1429, and YTHDF2) was significantly associated with prognosis, the immune microenvironment and treatment efficacy." (PMID 36831575, 2023). "A recent study also reported independent prognostic significance of ALKBH5, which is upregulated in glioma and associated with immune signalling, and inflammatory and metabolic pathways genes." (PMID 36831575, 2023). "ALKBH5 mRNA expression was associated with the prognosis of the glioma patients in the CGGA_325 and CGGA_693 datasets, but was independent of chemotherapy and/or radiotherapy." (PMID 35444654, 2022). "In the CGGA_325, CGGA_693, and TCGA datasets, high ALKBH5 expression levels were associated with shorter OS in primary glioma and LGG patients." (PMID 35444654, 2022). "Next, the relationship between ALKBH5 expression and specific genomic characteristics such as somatic mutations and copy number variations (CNVs) was analyzed in the TCGA glioma dataset." (PMID 35444654, 2022). "CGGA and TCGA database analyses showed that ALKBH5 expression levels were positively associated with glioma grades." (PMID 35444654, 2022). "The high ALKBH5-expressing glioma patients showed higher EGFR mutational rate compared to those with low ALKBH5 expression (24% vs. 15%)." (PMID 35444654, 2022). "In this study, gliomas with low ALKBH5 expression showed higher proportion (66%) of IDH1 mutations compared to those with high ALKBH5 expression (21%)." (PMID 35444654, 2022). "The function of ALKBH5 in gliomas was linked to cell proliferation and cell cycle progression." (PMID 38398118, 2024). "Moreover, the glioma tissues showed distinct somatic mutations and CNVs based on the expression levels of ALKBH5." (PMID 35444654, 2022). "Moreover, higher ALKBH5 mRNA and protein expression was associated with poorer prognosis of glioma patients." (PMID 35444654, 2022). "In gliomas, ALKBH5 stabilizes G6PD mRNA by demethylating m6A modification sites to activate the PPP91." (PMID 41522342, 2026). "Associations between glioma malignancy grade and the expression of m6 A writers (METTL3, METTL14, WTAP, and RBM15), the reader YTHDF, and erasers (ALKBH5 and FTO) are shown." (PMID 40382536, 2025). "Increased levels of phosphorylated ALKBH5 correlate with unfavorable clinical outcomes in glioma patients." (PMID 39990235, 2025). "In glioma cells, ALKBH5 demethylates FOXM1 mRNA at m6A sites within the 3′-UTR regions, facilitating the binding of the RNA-binding protein HuR to FOXM1 pre-mRNA in the nucleus, ultimately enhancing FOXM1 expression." (PMID 40186131, 2025). "The impact of ALKBH5 expression on the glioma tumor immune microenvironment has been explored by another study." (PMID 38398118, 2024). "The hypoxia-induced activity of ALKBH5 stabilizes transcripts like NEAT1, facilitating tumor-associated macrophage recruitment and immunosuppression, and enhances glioma cell growth by activating pathways like PPP." (PMID 38474421, 2024).
glioma (continued). "Given that ALKBH5 protein is quite stable in glioma cells, we focused on identifying deubiquitinases capable of impeding the ubiquitination-mediated degradation of ALKBH5." (PMID 38398118, 2024). "In fact, METTL3 and ALKBH5 are supposed to have opposite roles in regulating cell proliferation of glioma because METTL3 increases m6A level but ALKBH5 reduces m6A levels." (PMID 38398118, 2024). "Subsequently, overexpression experiments for METTL3, FTO, and ALKBH5 were conducted in glioma cells." (PMID 38405130, 2024). "Particularly, the erasers FTO and ALKBH5 exhibit a range of activities impacting various aspects of glioma biology." (PMID 38474421, 2024). "We also analyzed the ALKBH5 expression across gliomas with different WHO grades in the TCGA and CGGA cohorts, all the results indicated the highest expression of ALKBH5 in WHO IV gliomas." (PMID 38221546, 2024). "Its involvement in the proliferation, migration, and invasion of glioma cells has been well-established, and inhibitors targeting ALKBH5 reduce glioma cell migration and invasiveness." (PMID 38474421, 2024). "IGF2BP3 downregulated the expression of both m6A-associated writers (METTL3, METTL14) and erasers (FTO, ALKBH5), with a specific focus on FTO due to its more pronounced effect in both U87MG and GL261 glioma cell lines." (PMID 38167409, 2024). "MiR-193a-3p, a tumor suppressor, targets ALKBH5 exerting an anti-tumor effect by restraining the growth of glioma cells and promoting apoptosis via inhibiting the AKT2 pathway." (PMID 38072944, 2023). "ALKBH5 plays an important role in glioma cell proliferation and energy metabolism by activating the pentose phosphate pathway." (PMID 37964279, 2023). "ALKBH5 also functions in the maintenance of tumorigenicity, self-renewal, and tumorigenesis in glioma, promotes the radioresistance and invasion of glioma stem cells, and suppresses tumor progression." (PMID 35835441, 2023). "ALKBH5 expression is significantly increased in glioma cells and is involved in glioma cell proliferation." (PMID 37055798, 2023). "Real-time RT-PCR and western blot assays were performed to evaluate the baseline expression level of ALKBH5 in several glioma cell lines." (PMID 37325047, 2023). "A similar risk signature (ALKBH5, IGF2BP2, IGF2BP3, HNRNPA2B1, YTHDF1, YTHDF2, RBM15, and WTAP) was shown to be prognostic for glioma patients, and the expression of IGF2BP2 and IGF2BP3 was linked to tumour occurrence, development, and progression." (PMID 36831575, 2023). "This suggested that ALKBH5 expression regulated interferon signaling, lymphocyte activation, and activation of antigen-presenting cells in the gliomas." (PMID 35444654, 2022). "ALKBH5 mRNA levels were significantly higher in the U87-MG and U251-MG cell lines compared to the other glioma cell lines and were consistent with the results from the CCLE database." (PMID 35444654, 2022). "Our study suggested that ALKBH5 was a promising prognostic biomarker as well as a potential predictor of sensitivity to immunotherapy in several malignant tumors and glioma." (PMID 35444654, 2022). "Recurrent glioma patients showed a relatively higher ALKBH5 expression than primary glioma patients." (PMID 36566230, 2022). "In order to explore the m6A modification of glucose-6-phosphate dehydrogenase (G6PD) in the carcinogenesis of glioma, ALKBH5 was upregulated, which stimulated glioma cells to proliferate." (PMID 35625706, 2022). "In the present study, we elucidate the functional significance of ALKBH5 in immune responses via the regulation of PD-L1 in glioma." (PMID 36566230, 2022). "Analysis of 100 glioma cases discovered that glioma patients with high ALKBH5 expression levels had shorter OS compared with patients with low ALKBH5 expression level." (PMID 35444654, 2022). "ALKBH5 has been found to be highly expressed in glioma and can eliminate the m6A methylation of G6PD through ALKBH5, improving the proliferation ability of glioma cells." (PMID 35688823, 2022).
glioma (continued). "ALKBH5 mRNA was recognized as a miR-193a-3 target in both glioma and esophageal squamous cell carcinoma (ESCC), with its 3′UTR being a miR-193a-3p binding site." (PMID 35063010, 2022). "Cox regression analysis showed that ALKBH5 was an independent prognostic predictor in glioma patients." (PMID 35444654, 2022). "In vitro CCK-8, wound healing, Transwell and M2 macrophage infiltration assays as well as in vivo xenograft animal experiments were performed to determine the biological functions of ALKBH5 in glioma cells." (PMID 35444654, 2022). "The results showed that ALKBH5 mRNA and protein levels were upregulated compared to the corresponding normal tissues in multiple cancers including glioma." (PMID 35444654, 2022). "ALKBH5 is upregulated in glioma and of significance in regulating the metabolism and development of glioma." (PMID 35063010, 2022). "Overall, our analysis showed that ALKBH5 was a potential prognostic biomarker in various cancers, especially in glioma." (PMID 35444654, 2022). "Analysis of 100 glioma cases also showed that glioma patients with high ALKBH5 mRNA expression levels had shorter OS compared with patients with low ALKBH5 expression level." (PMID 35444654, 2022). "ALKBH5 expression levels showed positive correlation with various TIICs in the CGGA_325, CGGA_693, and TCGA glioma datasets; moreover, ALKBH5 expression correlated with the proportions of immune and stromal cells in the gliomas." (PMID 35444654, 2022). "In glioma, it was found that ALKBH5 remodeled the immune microenvironment via paraspeckle assembly and IL8 secretion yield." (PMID 36566230, 2022). "Since ALKBH5 expression shows positive correlation with tumor infiltration of immune cells in LGG, we further analyzed the relationship between ALKBH5 and tumor infiltrating immune cells in glioma using the ImmuCellAI and xCell databases." (PMID 35444654, 2022). "Mechanically, ALKBH5 deficiency impairs the YTHDF2-mediated stability of ZDHHC3 mRNA, thereby suppressing PD-L1 expression by accelerating PD-L1 degradation in glioma." (PMID 36566230, 2022). "Analysis of 100 glioma cases collected also showed that ALKBH5 expression level was positively correlated with glioma grade, which was consistent with our analysis results in CGGA and TCGA databases." (PMID 35444654, 2022). "We also investigated the upstream lncRNA-miRNA network that regulates ALKBH5 expression in gliomas and its effects on glioma progression." (PMID 35444654, 2022). "Overexpression of ALKBH5, an m6A demethylase, is related to poor prognosis in gliomas, consistent with our result." (PMID 35069679, 2021). "In this research, we aimed to study the function of exosomal circ_0072083 on TMZ resistance, and explore the regulatory network of circ_0072083/miR-1252-5p/ NANOG via competitive sponge and ALKBH5-mediated demethylation pathways in glioma." (PMID 33975615, 2021). "METTL14 has been reported as a tumor suppressor gene in GBM, and the erasers FTO and ALKBH5 are oncogenes in glioma." (PMID 33134160, 2020). "In summary, increased expression of ALKBH5 poses a significant obstacle to glioma therapy." (PMID 40469294, 2025). "Interestingly, ALKBH5 can also enhance glioma resistance to TMZ by stimulating the expression of SOX2, which coincides with the role of METTL3 in stabilizing GSCs through the promotion of SOX2 expression." (PMID 40469294, 2025). "Additionally, ALKBH5 can also impact the progression of gliomas by influencing the oxidative phosphorylation chain." (PMID 40469294, 2025). "Another eraser, ALKBH5, is also highly expressed in gliomas." (PMID 40469294, 2025). "Additionally, IOX1, an inhibitor of ALKBH5, has been shown to enhance the effectiveness of anti-PD-1 therapy in a mouse model of Glioma." (PMID 40958857, 2025). "The demethylase ALKBH5 has also been reported to facilitate the growth of gliomas." (PMID 40469294, 2025).
glioma (continued). "This suggests that the combination of anti-PD-1 therapy and ALKBH5 inhibition may represent a promising treatment strategy for glioma." (PMID 40958857, 2025). "Furthermore, depleting ALKBH5 expression is responsible for disrupting the tumorigenesis process of gliomas." (PMID 40469294, 2025). "Moreover, the upregulation of SOX2 mediated by METTL3 and the increased expression of ALKBH5 also enhance the radioresistance of glioma." (PMID 40469294, 2025). "Therefore, the combination of anti-PD-1 and anti-ALKBH5 is a promising therapeutic strategy for gliomas." (PMID 40469294, 2025). "Interestingly, in contrast to FTO expression, increased ALKBH5 expression in gliomas implies a poorer prognosis." (PMID 40469294, 2025). "We propose that USP3A‐induced activation of ALKBH5 may serve as a foundation for the development of more potent glioma treatments, given the important functional significance of ALKBH5 in GBM carcinogenesis." (PMID 40919129, 2025). "ALKBH5 has been documented to facilitate PD-L1-mediated immune evasion in glioma." (PMID 38398118, 2024). "In glioma, it was found that ALKBH5 not only affected tumor invasion ability, but also mediated tumor radioresistance, and the knockdown of ALKBH5 could play an active role in the treatment of glioma and improve its sensitivity to radiation therapy." (PMID 39033180, 2024). "Previous studies have shown that ALKBH5 may promote PD-L1-mediated immune evasion in glioma through m6A modification of ZDHHC." (PMID 38173044, 2024). "This implies that ALKBH5 expression may be involved in governing interferon signaling, lymphocyte activation, and activation of antigen-presenting cells within gliomas." (PMID 38398118, 2024). "Depletion of ALKBH5 resulted in heightened T cell infiltration within gliomas." (PMID 38398118, 2024). "Additionally, ALKBH5 influences immune responses in glioma, affecting cytokine expression and Programmed Death-Ligand 1 (PD-L1) protein levels." (PMID 38474421, 2024). "Given the roles of FTO and ALKBH5 in modulating cell death in glioma, focusing on how these m6A erasers influence apoptosis and ferroptosis, especially in GSCs, could be valuable." (PMID 38474421, 2024). "In glioma, a central nervous system malignancy, overexpression of ALKBH5 increases the transcriptional region m6A demethylation and thus enhances the mRNA stability of glucose-6-phosphate dehydrogenase (G6PD), the rate-limiting enzyme of the pentose phosphate pathway (PPP)." (PMID 37007161, 2023). "In addition, the Cox regression algorithm has been used to analyze 11 related prognostic genes, including ALKBH5, YTHDF1, YTHDF2, and HNRNPC in the CGGA to predict risk scores in glioma patients." (PMID 38072944, 2023). "The same combination but in glioma, while ALKBH5 was only screened as a target of miR‐193a‐3p." (PMID 36162823, 2023). "A recent study suggests that ALKBH5 is upregulated in glioma." (PMID 38072944, 2023). "Next, we analyzed ALKBH5 expression levels in various glioma cell lines by qRT-PCR." (PMID 35444654, 2022). "In vitro and in vivo experiments confirmed that ALKBH5 functioned as an oncogene in gliomas." (PMID 35444654, 2022). "In glioma, ALKBH5 could affect immunity, metabolism, cell cycle, DNA damage repair via CGGA_325, CGGA_693, TCGA and GSE93054 datasets." (PMID 35444654, 2022). "Moreover, ALKBH5 also affects the therapeutic effect of the first-line chemotherapy drug temozolomide in glioma." (PMID 35843942, 2022). "Furthermore, ALKBH5 expression levels correlated with the grades, subtypes, and clinical features of gliomas." (PMID 35444654, 2022). "Here, we found that deletion of ALKBH5 significantly inhibited the growth of glioma allografts, rescued the antitumoral immune response, and increased cytotoxic lymphocyte infiltration and proinflammatory cytokines in CSF while significantly suppressing PD-L1 protein expression." (PMID 36566230, 2022).
glioma (continued). "Furthermore, in vivo and in vitro experiments with glioma cells showed that ALKBH5 acted as an oncogene and promoted the growth, migration, and invasiveness of the glioma cells." (PMID 35444654, 2022). "We then further investigated the effects of ALKBH5 expression on the tumor immune microenvironment (TIM) of glioma by screening seven metagenes, namely, HCK, IgG, Interferon, LCK, MHC-I, MHC-II, and STAT1, which reflect the status of inflammation and immune responses." (PMID 35444654, 2022). "Therefore, ALKBH5 is a potential prognostic biomarker for patients with glioma and multiple cancer types." (PMID 35444654, 2022). "At present, there are few systematic studies on ALKBH5 in pan-cancer, especially in glioma." (PMID 35444654, 2022). "Consistently, IHC staining showed that PD-L1 expression was suppressed in ALKBH5-KO mice, which indicated that ALKBH5 might regulate PD-L1 expression post-translationally in glioma." (PMID 36566230, 2022). "In addition, AKT2 mRNA was identified as another critical target of ALKBH5 that contributes to the tumor-promoting effects of ALKBH5 in glioma cells." (PMID 35063010, 2022). "In our studies, high ALKBH5 expression was associated with clinical features such as IDH wildtype status, 1p/19q non-codeleted status, and demethylation of MGMT, all of which were related to poor prognosis in the glioma patients." (PMID 35444654, 2022). "In addition, analysis of the seven inflammation and immune related clusters suggested that high ALKBH5 expression activated the antigen-presenting cells and lymphocytes, and enhanced interferon signaling in the glioma tissues." (PMID 35444654, 2022). "This suggested that ALKBH5 expression modulated the recruitment of immune cells into the glioma and may affect the sensitivity of glioma patients to immunotherapy." (PMID 35444654, 2022). "Therefore, ZDHHC3 was selected as the candidate target of ALKBH5 in glioma for further investigation." (PMID 36566230, 2022). "ALKBH5 expression showed positive association with ICP receptors such as TNFRSF14, CD40, CD96 and CD200R1, and ICP ligands such as PDCD1LG2, CD70, TNFSF14, ICOSLG and CD274 in glioma tissues." (PMID 35444654, 2022). "In addition, circ-0072083 can also target miR-1252-5p to affect the expression of NANOG and ALKBH5 and regulate the drug resistance of glioma." (PMID 35688823, 2022). "This suggested that alterations in the ALKBH5 gene may regulate the initiation, growth and progression of various tumors, especially gliomas." (PMID 35444654, 2022). "Next, in order to further exploring the biological functions of ALKBH5 in glioma." (PMID 35444654, 2022). "Furthermore, tumor xenograft experiments showed that ALKBH5 knockdown suppressed the in vivo growth of glioma cells." (PMID 35444654, 2022). "Interestingly, we observed that the upregulation of ALKBH5 acts as a risk factor, while the downregulated of FTO acts as a risk factor in gliomas." (PMID 33264518, 2021). "The m6A demethylase ALKBH5 is one of important factors for TMZ resistance in glioma." (PMID 33975615, 2021). "Whether ALKBH5 plays a preferential role than FTO in glioma or whether they are specific for modification sites is worth further study." (PMID 33264518, 2021). "Moreover, ALKBH5 was also suggested to increase glioma stem cell radioresistance by regulating homologous recombination." (PMID 34496932, 2021). "As is visible in the violin plot, the mRNA expression levels of YTHDF2, YTHDF1, METTL3, RBM15 and HNRNPC were up‐regulated in glioma compared to normal tissues, whereas the expression levels of ALKBH5, WTAP, YTHDC2, ZC3H13 and METTL14, especially of FTO, were decreased in glioma." (PMID 32449290, 2020). "This also indicates that FTO and ALKBH5 may preferentially mediate demethylation of different methylation targets in glioma, and it is worth investigating in future studies." (PMID 30810537, 2019). "Therefore, ALKBH5 overexpression is indicative of an unfavorable prognosis in glioma patients." (PMID 38398118, 2024).